PIK3CG (phosphatidylinositol-4,5-bisphosphate 3-kinase catalytic subunit gamma)
Description:
Phosphoinositide-3-kinase (PI3K) that phosphorylates PtdIns(4,5)P2 (Phosphatidylinositol 4,5-bisphosphate) to generate phosphatidylinositol 3,4,5-trisphosphate (PIP3). PIP3 plays a key role by recruiting PH domain-containing proteins to the membrane, including AKT1 and PDPK1, activating signaling cascades involved in cell growth, survival, proliferation, motility and morphology. Links G protein coupled receptor activation to PIP3 production. Involved in immune, inflammatory and allergic responses. Modulates leukocyte chemotaxis to inflammatory sites and in response to chemoattractant agents. May control leukocyte polarization and migration by regulating the spatial accumulation of PIP3 and by regulating the organization of F-actin formation and integrin-based adhesion at the leading edge. Controls motility of dendritic cells. Together with PIK3CD is involved in natural killer (NK) cell development and migration towards the sites of inflammation. Participates in T-lymphocyte migration. Regulates T-lymphocyte proliferation, activation, and cytokine production. Together with PIK3CD participates in T-lymphocyte development. Required for B-lymphocyte development and signaling. Together with PIK3CD participates in neutrophil respiratory burst. Together with PIK3CD is involved in neutrophil chemotaxis and extravasation. Together with PIK3CB promotes platelet aggregation and thrombosis. Regulates alpha-IIb/beta-3 integrins (ITGA2B/ ITGB3) adhesive function in platelets downstream of P2Y12 through a lipid kinase activity-independent mechanism. May have also a lipid kinase activity-dependent function in platelet aggregation. Involved in endothelial progenitor cell migration. Negative regulator of cardiac contractility. Modulates cardiac contractility by anchoring protein kinase A (PKA) and PDE3B activation, reducing cAMP levels. Regulates cardiac contractility also by promoting beta-adrenergic receptor internalization by binding to GRK2 and by non-muscle tropomyosin phosphorylation. Also has serine/threonine protein kinase activity: both lipid and protein kinase activities are required for beta-adrenergic receptor endocytosis. May also have a scaffolding role in modulating cardiac contractility. Contributes to cardiac hypertrophy under pathological stress. Through simultaneous binding of PDE3B to RAPGEF3 and PIK3R6 is assembled in a signaling complex in which the PI3K gamma complex is activated by RAPGEF3 and which is involved in angiogenesis. In neutrophils, participates in a phospholipase C-activating N-formyl peptide-activated GPCR (G protein-coupled receptor) signaling pathway downstream of RASGRP4-mediated Ras-activation, to promote neutrophil functional responses (By similarity).
Synonyms: PI3Kgamma; p110gamma; IMD97; PI3CG; PI3K; PIK3; p120-PI3K
Tractability: Small molecule: an approved drug acts on it; a structure with a bound ligand is known; a high-quality ligand is known; it has a high-quality binding pocket; it belongs to a druggable protein family. Antibody: UniProt places it where antibodies can reach, with high confidence; its Gene Ontology location is reachable by antibodies, with high confidence; the Human Protein Atlas places it where antibodies can reach. PROTAC: it is named in the literature on targeted protein degradation; ubiquitination databases record sites on it; its protein half-life has been measured; a small molecule that binds it is known.
Target class: Enzyme; Transferase
Chemical probes: APITOLISIB (high quality), FMF-02-063-1 (high quality), NVP-CRL-457, PD080700, PD081434, PD082472, PD083206, PD084432, PD084694, PD085193, PD085329
Safety:
Unwanted effects reported when the protein is acted on. In parentheses: how it was acted on, where the effect was seen, and who reports it.
autoimmunity (inhibition; immune; source: Brennan et al. (2024))
breast cancer (activation; source: Brennan et al. (2024))
cardiac hypertrophy (activation; cardiovascular; source: Brennan et al. (2024))
colitis (inhibition; gastrointestinal; source: Brennan et al. (2024))
cytogenic abnormality (inhibition; cellular (genetic disorder); source: Brennan et al. (2024))
cytopenia (activation; blood; source: Brennan et al. (2024))
Decreased appetite (activation; source: Brennan et al. (2024))
fatigue (activation; source: Brennan et al. (2024))
glycosylated haemoglobin increase (activation; metabolic; source: Brennan et al. (2024))
Hyperglycaemia (inhibition; metabolic; source: Brennan et al. (2024))
hypertension (inhibition; cardiovascular; source: Brennan et al. (2024))
lymphopenia (activation; immune; source: Brennan et al. (2024))
nausea (activation; source: Brennan et al. (2024))
pancreatic steatosis (activation; pancreas; source: Brennan et al. (2024))
rash (inhibition; skin; source: Brennan et al. (2024))
weight loss (inhibition; source: Brennan et al. (2024))
heart disease (cardiovascular system; source: Force et al. (2011))
Gene: Protein-coding gene on chromosome 7 (106,865,278 to 106,908,980, forward strand). Ensembl gene ENSG00000105851.
Subcellular location: Cytoplasm; Cell membrane
Subcellular location (Human Protein Atlas): Plasma membrane; Cytosol
Pathways (Reactome):
Signal Transduction: Erythropoietin activates Phosphoinositide-3-kinase (PI3K); G beta:gamma signalling through PI3Kgamma; PI5P, PP2A and IER3 Regulate PI3K/AKT Signaling; PIP3 activates AKT signaling
Immune System: CD28 dependent PI3K/Akt signaling; Co-stimulation by ICOS
Disease: Constitutive Signaling by Aberrant PI3K in Cancer
Hemostasis: GPVI-mediated activation cascade
Metabolism: Synthesis of PIPs at the plasma membrane
Gene Ontology:
Molecular function: 1-phosphatidylinositol-3-kinase activity; 1-phosphatidylinositol-4,5-bisphosphate 3-kinase activity; 1-phosphatidylinositol-4-phosphate 3-kinase activity; ephrin receptor binding; identical protein binding; protein binding; protein serine kinase activity; protein kinase activity; kinase activity; protein serine/threonine kinase activity
Biological process: G protein-coupled receptor signaling pathway; phosphatidylinositol 3-kinase/protein kinase B signal transduction; phosphatidylinositol phosphate biosynthetic process; positive regulation of endothelial cell migration; positive regulation of MAP kinase activity; positive regulation of phosphatidylinositol 3-kinase/protein kinase B signal transduction; positive regulation of Rac protein signal transduction; regulation of angiogenesis; sphingosine-1-phosphate receptor signaling pathway; adaptive immune response; cell migration; dendritic cell chemotaxis; immune response; inflammatory response; innate immune response; mast cell degranulation; natural killer cell chemotaxis; negative regulation of cardiac muscle contraction; neutrophil chemotaxis; neutrophil extravasation; phosphatidylinositol-3-phosphate biosynthetic process; phosphatidylinositol-mediated signaling; phospholipase C-activating G protein-coupled receptor signaling pathway; platelet aggregation; positive regulation of cytokine production; and 5 more
Cellular component: cytoplasm; cytosol; membrane; phosphatidylinositol 3-kinase complex, class IA; phosphatidylinositol 3-kinase complex, class IB; plasma membrane
Genetic constraint (gnomAD): Loss-of-function variants: 45 observed, 87.95 expected, observed/expected ratio (o/e) 0.51, 90% interval 0.4 to 0.66. The upper end of that interval is the gene's LOEUF score, 0.66, which puts it in group 2 of 6, group 1 being the genes least tolerant of losing a copy. Missense variants: 1,169 observed, 1,344.3 expected, observed/expected ratio (o/e) 0.87, 90% interval 0.83 to 0.91. Synonymous variants: 512 observed, 531.04 expected, observed/expected ratio (o/e) 0.96, 90% interval 0.9 to 1.04.
Gene-disease validity (ClinGen):
ClinGen rates the evidence that PIK3CG causes each of these diseases.
immunodeficiency 97 with autoinflammation (autosomal recessive): Moderate. An autosomal recessive complex immunologic disorder with variable features.
Homologues: Orthologues: chimpanzee PIK3CG (99% identical), macaque PIK3CG (99% identical), pig PIK3CG (95% identical), rabbit PIK3CG (94% identical), mouse Pik3cg (94% identical), rat Pik3cg (94% identical), guinea pig PIK3CG (93% identical), dog PIK3CG (92% identical), tropical clawed frog pik3cg (75% identical), zebrafish pik3cg (71% identical), Drosophila melanogaster Pi3K92E (28% identical), Caenorhabditis elegans age-1 (25% identical), and 2 more. Paralogues in human: PIK3CA (32% identical), PIK3CD (30% identical), PIK3CB (30% identical), PIK3C2A (26% identical), PIK3C2B (25% identical), PIK3C2G (21% identical), PI4KA (19% identical), PIK3C3 (19% identical), PI4KB (13% identical).
Diseases named in the same sentence as PIK3CG in open-access papers:
PIK3CG is named in the same sentence as 176 diseases in open-access papers, as found by Europe PMC text mining. Sharing a sentence is not in itself a finding about the gene and the disease. The quoted sentences say what the papers report.
breast cancer (45 papers, 2005 to 2026). A primary or metastatic malignant neoplasm involving the breast. "IKZF1 is known to be an important factor in acute lymphoblastic leukemia, IRF4 drives tumor growth in several lymphoid malignancies, and PIK3CG is closely associated with claudin‐low breast cancer migration." (PMID 38506253, 2024). "PIK3CG is overexpressed in numerous invasive human breast tumors, and its expression levels are associated with the metastatic potential of breast cancer cell lines." (PMID 39850811, 2024). "In addition, about three-quarters of breast cancers have an increased expression of PIK3CG, which encodes for p110γ." (PMID 34769309, 2021). "While our previous work demonstrated the oncogenic role of MFNG in claudin-low breast cancer by modulating the Pik3cg-driven Notch signaling, the precise mechanism as to how MFNG can be regulated in TNBC has not been reported elsewhere." (PMID 35804829, 2022). "PIK3CG is aberrantly expressed in many invasive human breast tumors and its expression level correlates with metastatic potential of breast cancer cell lines." (PMID 26682266, 2015). "Previous research suggests that PIK3CG may enhance breast cancer cell migration and invasion while preventing anoikis." (PMID 39850811, 2024). "Specifically, the identification of miRNAs such as miR-129, miR-19a-3p, and miR-30d-5p, as well as proteins like COL4A1, MAPK3, PIK3CG, and mTOR, provides valuable insights into the molecular mechanisms underpinning aggressive breast cancer subtypes, such as TNBC." (PMID 39850811, 2024). "However, recent studies demonstrated that PIK3CG promotes tumor progression in prostate cancer and breast cancer." (PMID 36110953, 2022). "In addition, Src (SRC), VEGFR2 (KDR), IGF1R and PI3Kγ (PIK3CG) have already been successful targets in breast cancer therapy." (PMID 33246450, 2020). "We showed that pharmacologic inhibition of PI3Kγ in CLBC cell lines blocked migration and tumorsphere formation, suggesting that Mfng-induced Pik3cg contributes to breast cancer aggressiveness by promoting cell migration and invasion, as well as maintaining cancer cell stemness." (PMID 26682266, 2015). "PIK3CG inhibitors, including duvelisib and IPI-549, exhibit promise in leukemia and breast cancer, respectively." (PMID 39877641, 2025). "Previously, we reported that MFNG was highly expressed in claudin-low breast cancer (CLBC) and promoted cell migration, proliferation, and tumorigenicity by modulating Notch activation by directly targeting phosphoinositide kinase (PIK3CG)." (PMID 35804829, 2022). "Identification of Pik3cg as a Notch target prompts a PI3Kγ-targeting strategy for the treatment of CLBC and perhaps other poor prognosis breast cancers." (PMID 26682266, 2015). "We showed that miR-190a-3p, a key regulator of gene expression and pathways important in breast cancer, is potentially involved in the regulation of COL4A1, MAPK3, PIK3CG, and PIK3R1, all of which are integral to pathways associated with breast cancer progression." (PMID 39850811, 2024).
prostate carcinoma (17 papers, 2013 to 2025). A carcinoma that arises from epithelial cells of the prostate gland. "PIK3CG may represent a new therapeutic target in metastatic castration-resistant prostate cancer." (PMID 35872841, 2022). "TIMER was used for correlation analysis and it indicated that UBASH3B was significantly correlated with LCP2 (p = 3.37e-40, cor = 0.547), PIK3CG (p = 2.44e-38, cor = 0.536), and BIRC3 (p = 0, cor = 0.534) in prostate cancer." (PMID 32010618, 2019). "Moreover, LCP2, PIK3CG, and BIRC3 were also positively correlated with these six types of immune cells in prostate cancer." (PMID 32010618, 2019). "However, a previous study had demonstrated the importance of PIK3CG in the progression and metastasis of prostate cancer rather than in hepatoma." (PMID 35872841, 2022). "The “prostate cancer” pathway also comprises genes that are relatively specific to the (human) prostate (CREB3L4, KLK2, NKX3-1 and SRD5A2), proto-oncogenes (EGFR, NRAS, PDGFRA and PDGFRB), and druggable candidates (CDKN1A, CTNNB1, EGFR, NRAS, PDGFRA, PDGFRB, PIK3CD and PIK3CG)." (PMID 34768937, 2021). "Finally, the “prostate cancer” pathway also includes DEGsSD that are relatively specific to the (human) prostate (SRD5A2, KLK2, NKX3-1 and CREB3L4), proto-oncogenes (EGFR, PDGFRA, PDGFRB, NRAS) and druggable candidates (PIK3CD, CTNNB1, PIK3CG, CDKN1A)." (PMID 34768937, 2021).
lung cancer (15 papers, 2013 to 2025). A malignant neoplasm involving the lung. "In particular, PIK3CG activation is intimately linked to tumor cell proliferation in non–small cell lung cancer, and its mutation may result in drug resistance." (PMID 41141246, 2025). "Furthermore, mutations and amplifications of PIK3CG were commonly detected in a range of malignancies, including melanoma, as well as prostate, uterine, gastric, and lung cancers." (PMID 39468696, 2024). "exhibits significant anti-lung cancer potential by targeting key genes such as PIK3CG, SRC, and JAK3, as well as by modulating the PI3K-Akt signaling pathway and apoptosis-related genes." (PMID 40331978, 2025). "Although the prevalence and functional relevance of mutations in PI3Ks other than p110α are considered limited it is worth mentioning that significant recurrent mutations have been seen in both PIK3CG (9.7%) and PIK3C2B (12.9%), the gene encoding for the class II isoform PI3K-C2β, in lung cancer." (PMID 25360116, 2014). "Network pharmacological analysis identified PIK3CG, SRC, JAK3, AKT2, and PRKCA as key potential targets of peiminine in lung cancer treatment." (PMID 40331978, 2025). "Furthermore, we found increased mRNA of PIK3CB, PIK3CD, PIK3CG, BCL2, TUBB3 in ALK-positive lung cancer, which suggested activation of PI3K/AKT signaling pathway." (PMID 34234236, 2021). "Additionally, the identified targets (PIK3CG, SRC, JAK3, AKT2, and PRKCA) may function as possible biomarkers for predicting lung cancer prognosis and guiding personalized therapy." (PMID 40331978, 2025).
melanoma (13 papers, 2016 to 2025). A malignant, usually aggressive tumor composed of atypical, neoplastic melanocytes. "We queried the melanoma cohort to identify the gene expression levels for PIK3CG in primary and metastatic melanoma tissues." (PMID 32891176, 2020). "PIK3CG mutation and amplification are frequent in multiple malignancies, including 9–11% of melanomas and uterine, stomach and squamous cell lung cancers, while genetic alterations in PIK3R5 and PIK3R6 are prevalent in uterine cancer and melanoma, occurring in 4–8% of cases." (PMID 32630372, 2020). "Phosphatidylinositol-4,5-bisphosphate 3-kinase catalytic subunit γ (PIK3CG) was identified in multiple upregulated pathways for the metastatic brain tumors and gene expression was significantly increased in metastatic melanoma samples in comparison to primary melanoma from TCGA data." (PMID 32891176, 2020).
colorectal cancer (12 papers, 2011 to 2025). A primary or metastatic malignant neoplasm that affects the colon or rectum. "Immunohistochemistry revealed a decreased PIK3CG expression in 85% of colorectal cancers, which was associated with tumor invasiveness and metastasis." (PMID 34552612, 2021). "The genes encoding for the beta (PIK3CB) and gamma (PIK3CG) catalytic sub-units and the regulatory sub-unit 1 (PIK3R1) of PI3K were more commonly mutated in CDX2-suppressed colorectal cancers." (PMID 39452477, 2024). "The inhibition of the PIK3CG gene is pivotal in dampening the PAM signaling pathway, thereby hindering tumorigenesis and the advancement of colorectal cancers." (PMID 39877641, 2025). "Silencing the PIK3CG inhibits the PI3K-Akt/PKB pathway, resulting in tumorigenesis and progression of colorectal cancer." (PMID 36110953, 2022).
ovarian carcinoma (10 papers, 2012 to 2025). A malignant neoplasm originating from the surface ovarian epithelium. "The increased PIK3CG gene copy number has been documented in ovarian cancer, as well." (PMID 23259526, 2012). "Network pharmacology analysis indicated that quercetin, luteolin, and baicalein may be important anticancer components in HD-SB, potentially acting on targets such as EGFR, MAPK1, VEGFA, and PIK3CG to inhibit ovarian cancer growth and migration via focal adhesion pathways." (PMID 39274982, 2024). "HSP90AA1, CDK2, and PIK3CG might be potential targets of SMB in inhibiting ovarian cancer." (PMID 36483919, 2022). "The DNA structure variation of PIK3CG may strike the occurrence of ovarian cancer." (PMID 33218349, 2020). "In addition, the PI3K-Akt signaling pathway might be the main pathway for SMB to inhibit ovarian cancer because the significant genes HSP90AA1, CDK2, and PIK3CG in this pathway receive the action of multiple ingredients in SMB." (PMID 36483919, 2022).